CNKSR2 (connector enhancer of kinase suppressor of Ras 2)
Diseases named in the same sentence as CNKSR2 in open-access papers (continued):
Sharing a sentence is not in itself a finding about the gene and the disease.
squamous cell carcinoma (1 paper, 2024). A carcinoma arising from squamous epithelial cells. "The expression of CNKSR2 was significantly lower in CESC patients than in normal controls in subgroups based on T stage, clinical stage, histological type and keratinizing squamous cell carcinoma." (PMID 38169557, 2024). "Additionally, high CNKSR2 expression was found in CESC patients with histological type (P<0.001) and keratinizing squamous cell carcinoma (P = 0.026) according to logistic analysis." (PMID 38169557, 2024).
thyroid papillary carcinoma (1 paper, 2024). "CNKSR2 expression in patients with thyroid papillary carcinoma is often increased, particularly in in vitro experiments revealing that the knockdown of CNKSR2 inhibits ERK phosphorylation and Notch signaling transduction decreases, resulting in damaged tumor proliferation." (PMID 38169557, 2024).
X-linked syndromic mental retardation (1 paper, 2022). "CNKSR2 is now considered as a causative gene of the Houge type of X-linked syndromic mental retardation (MRXHG), an XLID recorded in OMIN in 2017 (#301008)." (PMID 35053419, 2022).
cancer (9 papers, 2018 to 2025). A tumor composed of atypical neoplastic, often pleomorphic cells that invade other tissues. "Altogether, these findings motivate the investigation of the therapeutic efficacy of Smurf2 knockdown in treating CNKSR2-addicted cancers more effectively either as an individual therapy or in combination with already existing chemotherapy and/or radiotherapy." (PMID 29534682, 2018). "Previous studies have revealed that the Smurf2 E3 ubiquitin ligase may induce CNKSR2 in cancer cells and participate in cancer cell proliferation." (PMID 38169557, 2024). "Overall, the expression pattern of Smurf2 and CNKSR2 showed a significant positive association (P < 0.001) between each other among non-malignant and malignant tumors." (PMID 29534682, 2018). "However, when PR was moderate/intense, only 24.19 and 29.03% of malignant tumors showed moderate/intense expression of Smurf2 and CNKSR2." (PMID 29534682, 2018). "Interestingly, among malignant tumors, 51 out of 62 cases (82.26%) showed moderate/intense expression of CNKSR2 when Smurf2 expression was moderate/intense." (PMID 29534682, 2018). "As for the DNA methylation, the cancers and the corresponding genes with hypermethylation were as follows: BRCA: VWF and ITGB3; COAD: QKI, DUSP9, and CNKSR2; KIRC: CNKSR1; PRAD: VWF, LMNA, and ITGB3; UCEC: ITGB3 and APBBAIP." (PMID 38217548, 2024). "While further work is required to determine if, and how, the CNKSR2 locus is derepressed in non-neuronal cancer cells, our study suggests that aberrant expression of CNK2A confers a motile phenotype by hijacking ARF6 signalling." (PMID 37322019, 2023). "Further we analyzed the association between Smurf2, CNKSR2, ER, PR, and HER2 expression with non-malignant and malignant tumors using multiple logistic regression analysis taking non-malignant tumors as the reference." (PMID 29534682, 2018). "Only 5 out of 62 malignant tumors (8.06%) showed a no/mild expression of CNKSR2 when Smurf2 expression was moderate/intense." (PMID 29534682, 2018). "Concomitantly, CNKSR2 expression also exhibited a similar pattern with 54 out of 62 malignant tumors (87.10%) showing moderate to intense expression of CNKSR2 compared with non-malignant samples, where only 5 out of 22 cases (22.73%) were found to have high expression of CNKSR2 (P < 0.001)." (PMID 29534682, 2018). "Similarly, when PR was no/mild, 66.13 and 58.06% of malignant tumors showed moderate/intense expression of Smurf2 and CNKSR2." (PMID 29534682, 2018). "Interestingly, we observed a statistically significant association between Smurf2 and CNKSR2 expression with the ER, PR, and HER2 status of non-malignant and malignant tumors." (PMID 29534682, 2018). "Our studies have shown that when ER was no/mild, 61.29 and 58.06% of malignant tumors showed moderate/intense expression of Smurf2 and CNKSR2, while only 29.03% of malignant tumors showed moderate/intense expression of Smurf2 and CNKSR2 when ER was moderate/intense." (PMID 29534682, 2018). "Contrarily, we observed that when HER2 was no/mild, only 40.32 and 38.71% of malignant tumors showed moderate/intense expression of Smurf2 and CNKSR2 whereas 50.00 and 48.39% of malignant tumors showed moderate/intense expression of Smurf2 and CNKSR2 when HER2 was moderate/intense." (PMID 29534682, 2018). "We reported previously that Smurf2 knockdown significantly downregulated the CNKSR2 protein levels in MDA-MB-231, MCF-7, SW480, and SCC131 cancer cell lines without any effect on CNKSR2 mRNA, suggesting that Smurf2 controls the CNKSR2 protein level possibly through proteolytic regulation." (PMID 29534682, 2018). "We next observed that the expression levels of Smurf2 and CNKSR2 in relation with the hormonal (ER and PR) and HER2 status of breast tissue samples showed a statistically significant difference among non-malignant and malignant tumors." (PMID 29534682, 2018).
tumor (6 papers, 2014 to 2024). "Simultaneously, we also analyzed the expression levels of CNKSR2 in the same set of samples and observed a statistically significant association with tumor grade (P < 0.001)." (PMID 29534682, 2018). "Importantly, Smurf2 and CNKSR2 expression has been associated with features of tumor aggressivity, ER and PR negativity and HER2 overexpression." (PMID 29534682, 2018). "Mice injected with control cells displayed a strong bioluminescent signal in the abdominal region after 3 weeks, indicative of metastatic tumour formation, that was drastically reduced by both CNKSR2 KO or SAMD12 KO." (PMID 37322019, 2023). "One study has shown that six of such genes show increased loss-of-function mutations in male tumor diseases (ATRX, CNKSR2, DDX3X, KDM5C, KDM6A, and MAGEC3)." (PMID 32629877, 2020). "In the present study, we first revealed that CNKSR2 was correlated with CESC tumor tissue." (PMID 38169557, 2024). "This correlation of Smurf2 with CNKSR2 may explain the role of Smurf2 in proliferation and invasiveness of tumor cells." (PMID 25191523, 2014). "Therefore, we hypothesized that CNKSR2 might mediate signal transduction in tumors through synaptic aggregation, thereby inhibiting tumor development." (PMID 38169557, 2024). "KO of CNKSR2 or SAMD12 did not affect the size of liver tumours and liver weight, suggesting that reduced tumour burden caused by loss of CNK2 or SAMD12 is due to impaired cell invasion and not tumour growth after colonization." (PMID 37322019, 2023).
neurodevelopmental disorder (5 papers, 2019 to 2024). A behavioral and cognitive disorder with onset during the developmental period that involves impaired or aberrant development of intellectual, motor, or social functions. "Previous research indicates that mutations in Cnksr2 linked to neurodevelopmental disorders, including EAS, involve significant deletions and nonsense mutations, resulting in a loss of function." (PMID 39694826, 2024). "Mutations in CNKSR2 have been described in patients with neurodevelopmental disorders characterized by childhood epilepsy, language deficits, and attention problems." (PMID 33298018, 2020). "Additionally, we summarized the association between the gene variations of CNKSR2 and neurodevelopmental disorders." (PMID 35053419, 2022). "In this review, we firstly summarize the molecular characteristics and biological functions of CNKSR2 and then we describe the involvement of CNKSR2 in neurodevelopmental disorders." (PMID 35053419, 2022). "In this review, we summarized molecular features, neuronal function, and neurodevelopmental disorder-related variations of CNKSR2." (PMID 35053419, 2022). "The variant of CNKSR2 in XLID was found in 2012, and reports describing the implication of CNKSR2 in neurodevelopmental disorders are increasing now." (PMID 35053419, 2022). "The exact biological roles of CNKSR2 in vivo are largely unknown and further studies to clarify the functions of CNKSR2 in the brain may contribute to a better understanding of the pathophysiology of neurodevelopmental disorders." (PMID 35053419, 2022).
neurologic disease (2 papers, 2023 to 2024). "Recent studies have implicated GLS, RAI1, GIPC1, MED15, EP400, MEF2A, and CNKSR2 in neurological diseases, with GLS, GIPC1, MED15, RAI1, and MEF2A sharing the same repeat loci reported in this study." (PMID 38871700, 2024).
CNKSR2 also shares sentences with these, for which no sentence is quoted: coccidiosis (2 papers); Alpha-thalassemia (1); Ataxia (1); bipolar disorder (1); brain disorder (1); breast adenocarcinoma (1); carcinoma-in-situ (1); channelopathy (1); colon cancer (1); early-onset epilepsy (1); early-onset epileptic encephalopathy (1); endometrial carcinoma (1); Epileptic encephalopathy (1); gastric cancer (1); glioblastoma (1); infection (1); Intellectual Disability Syndrome (1); invasive breast carcinoma (1); invasive ductal carcinoma (1); language disorder (1); lung adenocarcinoma (1); oral cancer (1); osteosarcoma (1); ovarian serous cystadenocarcinoma (1); pancreatic cancer (1); paraganglioma (1); pheochromocytoma and (1); prostate carcinoma (1); rectal cancer (1); Seizure (1).
A further 4 diseases each share a sentence with CNKSR2 in 1 paper.